CRHBP (corticotropin releasing hormone binding protein)
Description:
Specifically binds and inactivates the corticotropin-releasing hormone (CRH) and urocortin-1 (UCN) hormones, thereby inhibiting the hypothalamus-pituitary-adrenal axis and preventing corticotropin hormone (ACTH) production. May be required to prevent inappropriate pituitary-adrenal stimulation in pregnancy.
Synonyms: CRF-BP; CRFBP
Tractability: Antibody: its Gene Ontology location is reachable by antibodies, with high confidence; UniProt places it where antibodies can reach, with medium confidence; UniProt predicts a signal peptide or a membrane-spanning region. PROTAC: a small molecule that binds it is known.
Safety:
Unwanted effects reported when the protein is acted on. In parentheses: how it was acted on, where the effect was seen, and who reports it.
stress-induced alcohol cravings (source: ClinPGx)
Gene: Protein-coding gene on chromosome 5 (76,953,044 to 76,981,158, forward strand). Ensembl gene ENSG00000145708.
Subcellular location: Secreted
Pathways (Reactome):
Signal Transduction: Class B/2 (Secretin family receptors)
Gene Ontology:
Molecular function: corticotropin-releasing hormone binding; protein binding; receptor ligand inhibitor activity; peptide binding
Biological process: behavioral response to ethanol; cellular response to estradiol stimulus; cellular response to estrogen stimulus; cellular response to potassium ion; cellular response to tumor necrosis factor; female pregnancy; hormone-mediated signaling pathway; negative regulation of corticotropin secretion; regulated exocytosis; regulation of cellular response to stress; regulation of corticotropin secretion; cellular response to calcium ion; cellular response to cAMP; cellular response to cocaine; cellular response to gonadotropin-releasing hormone; cellular response to xenobiotic stimulus; learning or memory; regulation of NMDA receptor activity; signal transduction; synaptic transmission, dopaminergic; maternal aggressive behavior
Cellular component: endoplasmic reticulum; extracellular region; Golgi apparatus; secretory granule; axon terminus; dendrite; dense core granule; microtubule; multivesicular body; nucleus; perikaryon; secondary lysosome; varicosity
Genetic constraint (gnomAD): Loss-of-function variants: 18 observed, 34.85 expected, observed/expected ratio (o/e) 0.52, 90% interval 0.36 to 0.77. The upper end of that interval is the gene's LOEUF score, 0.77, which puts it in group 3 of 6, group 1 being the genes least tolerant of losing a copy. Missense variants: 326 observed, 427.3 expected, observed/expected ratio (o/e) 0.76, 90% interval 0.7 to 0.84. Synonymous variants: 153 observed, 161.15 expected, observed/expected ratio (o/e) 0.95, 90% interval 0.83 to 1.09.
Homologues: Orthologues: chimpanzee CRHBP (100% identical), macaque CRHBP (98% identical), pig CRHBP (93% identical), mouse Crhbp (87% identical), dog CRHBP (87% identical), rat Crhbp (85% identical), guinea pig CRHBP (83% identical), tropical clawed frog crhbp (67% identical), zebrafish crhbp (63% identical), rabbit CRHBP (61% identical), Drosophila melanogaster CG15537 (25% identical).
Diseases named in the same sentence as CRHBP in open-access papers:
CRHBP is named in the same sentence as 44 diseases in open-access papers, as found by Europe PMC text mining. Sharing a sentence is not in itself a finding about the gene and the disease. The quoted sentences say what the papers report.
Anxiety (10 papers, 2008 to 2024). Intense feelings of nervousness, tension, or panic often arise in response to interpersonal stresses. "In the mouse with CRHBP deficiency, a significant loss in body weight and an increase in anxiety-like behavior have been detected, thus supporting that CRHBP is a negative regulator in CRH signaling." (PMID 36292565, 2022). "Early studies showed that CRHBP deficiency (–/–) in mice contributed to increased stress and anxiety-like behaviors compared to wildtype littermates." (PMID 34912198, 2021). "CRHBP polymorphisms have also been related to severity of stress-induced alcohol craving and have been hypothesized to impact anxiety or drinking in alcohol-dependent individuals." (PMID 29497387, 2018). "Thus, the CRHBP is considered candidate gene for anxiety and addiction and possibly required in NMDAR-mediated excitatory postsynaptic currents in the VTA area." (PMID 37971544, 2024). "In male rodents, the stimulation of these interneurons leads to the release of CRHBP and the reduction of CRH activity and anxiety, while in female rodents CRHBP was not able to effectively inhibit CRH activity, which may be due to higher levels of CRH in paraventricular nuclei (PVN)." (PMID 36004833, 2022).
depression (9 papers, 2012 to 2024). "Investigation of CRHBP genetic polymorphisms can provide additional insight on the role that CRHBP variants play in genetic risk for comorbid depression and other psychiatric conditions." (PMID 34912198, 2021). "SNPs in CRHBP have also been associated with vulnerability for unipolar depression and stress-induced alcohol craving." (PMID 23077729, 2012). "The CRHBP gene is linked to the stress pathway, which has been associated with the development of several substance use disorders (SUDs), relapse susceptibility, and major depressive disorders." (PMID 37971544, 2024). "Of thirteen depression‐associated DRPs, seven proteins including DDC, FGFR2, KIBRA, MED22, OLIG1, RAI1, SLIT2 were upregulated, whereas six proteins including COX3, CRHBP, CSMD1, FSTL1, GRIK4, and LMTK3 were downregulated." (PMID 39373701, 2024). "Other genes near the variant also showed involvement in brain development (ZBED3), in GABAergic interneurons in the prefrontal cortex, hippocampal abnormalities, depression, and other neuropsychiatric disorders such as substance abuse (CRHBP)." (PMID 37337823, 2023). "A recent study found that in major depressive disorder and in persistent depressive disorder, specific single nucleotide polymorphisms and haplotypes in genes related to the corticotrophin-releasing hormone (CRHBP, CRHR1) and melanocortins (POMC) predicted the non-responder status." (PMID 31507525, 2019).
alcohol dependence (5 papers, 2012 to 2023). Physical and psychological dependence on alcohol. "Genetic associations of CRF signaling to alcohol phenotypes in humans is not restricted to CRHR1, because several studies link genetic variants in CRHBP, which encodes the CRF-binding protein, to features of alcohol dependence." (PMID 29497387, 2018). "Analysis of a different CRHR1 SNP (rs110402) in schizophrenia patients shows that the T allele interacts with a G allele in a CRHBP SNP (rs3811939) to double the risk of comorbid alcoholism in these patients." (PMID 23077729, 2012). "This suggests that a particular combined genotype of rs110402 in CRHR1 and rs3811939 in CRHBP plays an important role in alcoholism through gene-by-gene interaction." (PMID 25802844, 2015). "Interactions between CRHBP and CRHR1 polymorphism have been observed to increase suicide attempts and alcoholism in schizophrenic patients." (PMID 23077729, 2012). "Association analysis revealed that the SNPs in CRHR1 and CRHBP (corticotropin-releasing hormone binding protein) are associated with blood mRNA concentrations in both alcohol-dependent patients and nondependent controls." (PMID 25802844, 2015). "Among the genes identified include those previously reported for nicotine and alcohol dependence (CHRNA9 and CRHBP)." (PMID 37915799, 2023).
alcohol use disorder (5 papers, 2015 to 2021). "Additional gene variants of CRHR1 and CRHBP have been associated with various mood and anxiety disorders as well as alcohol use disorders [reviewed in Ref." (PMID 29497387, 2018). "CRHBP is a gene involved in the HPA-axis found to have links with suicide attempt and alcohol use disorder comorbidities in schizophrenia." (PMID 34573345, 2021). "Individual CRHBP and CRHR1 SNPs have been shown to coordinately predict alcohol use disorder comorbidity in a panel of schizophrenic patients." (PMID 29497387, 2018).
renal cell carcinoma (5 papers, 2016 to 2024). "Overexpression of CRHBP (corticotropin-releasing hormone-binding protein) was shown to promote apoptosis in renal cell carcinoma via activating the nuclear factor (NF)-κB signaling pathway." (PMID 35565057, 2022).
schizophrenia (5 papers, 2016 to 2025). A major psychotic disorder characterized by abnormalities in the perception or expression of reality. "The association between CRHR1 and CRHBP genes with severity of suicidal behavior was found in patients with schizophrenia." (PMID 28358316, 2017). "Gene coding for the CRH binding protein (CRHBP) was investigated in schizophrenia." (PMID 28358316, 2017).
renal carcinoma (4 papers, 2013 to 2022). A carcinoma arising from the epithelium of the renal parenchyma or the renal pelvis. "Tumor cell lines showed 5-aza-2 ́-deoxycytidine dependent reduction of methylation and re-expression of CRHBP was associated with altered cellular invasiveness of renal cancer cells in real-time impedance invasion assays." (PMID 27695045, 2016). "Comparison of methylation in normal and paired renal cancer tissue specimens revealed hypermethylation of the CRHBP CGI in tumors (p<1*10−12)." (PMID 27695045, 2016). "Real–time impedance analyses of cells grown on top of microelectrodes were applied to measure possible effects of CRHBP on proliferation and invasiveness of the renal cancer cell lines 786-O, RCC-GS and RCC-HS." (PMID 27695045, 2016). "The objective of our study was to assess the expression of the CRHBP mRNA and protein in renal cancer." (PMID 23607589, 2013). "On the other hand, ectopic expression of CHRBP also showed alteration, i.e. reduction of cellular invasiveness thus providing further evidence that invasive behavior of renal cancer cells may be affected by CRHBP." (PMID 27695045, 2016). "Whether Ucn and CRHBP levels in blood and urine become altered and possibly affect renal cancer progression or can serve as biomarker therefore appear as further relevant questions remaining to be clarified in future studies." (PMID 23607589, 2013). "Considering that previous analyses support the relevance of the UCN system for human carcinogenesis including also renal cancer, we hypothesize that alteration of CRHBP as a putative modulator of UCN levels may also contribute to the development and course of cc-RCC." (PMID 23607589, 2013). "In recent years, with the deepening of epigenetic research, the epigenetic regulatory mechanisms of renal cancer, especially DNA methylation, are often used to predict the survival time of renal cancer, including DAB2IP, RCVRN, CRHBP, AR, and CDO1." (PMID 32733620, 2020).
hepatocellular carcinoma (3 papers, 2020 to 2024). A malignant tumor that arises from hepatocytes. "Recent studies showed that corticotropin releasing factor binding protein (CRHBP) expression is linked with high α-fetoprotein level in patients with hepatocellular carcinoma (HCC), and HCC patients with low CRHBP expression have poor overall survival rate." (PMID 31570754, 2020).
anxiety disorder (2 papers, 2018 to 2021). A category of psychiatric disorders which are characterized by anxious feelings or fear often accompanied by physical symptoms associated with anxiety. "Polymorphisms in CRHBP, which is hypothesized to modulate the amount of CRF or urocortin-1 available to interact with its receptors, have been related to decreased EEG alpha wave power, a feature observed in alcoholics, and are more prevalent in alcoholics with comorbid anxiety disorders." (PMID 29497387, 2018).
bipolar disorder (2 papers, 2019 to 2025). A disorder of the brain that causes unusual shifts in mood, energy, activity levels and the ability to carry out day-to-day tasks. "Among these were BDNF, VGF, WFS1, DUSP6, CRHBP, MAOA, and RELN, which have previously been implicated in bipolar disorder." (PMID 31114610, 2019).
breast carcinoma (2 papers, 2010 to 2023). "Another biologically relevant gene that we found to be differentially expressed in breast cancer was corticotropin releasing hormone binding protein (CRHBP)." (PMID 21059268, 2010). "Subsequent hierarchical clustering suggested that a number of those genes (including PPARG, FGF2, APOB, CRHBP, CETP, and RXRG) were significantly associated with breast cancer that appeared repeatedly in different GO-terms." (PMID 21059268, 2010). "This analysis indicates that the predicted PTB-related genes including ICAM1, CRHBP, PLAGL1, EGR2, CNTLN, and DKK1 play an important role in preforming biological activities associated with PTB, infant disease, and possibly breast cancer, due to the gestational age-induced." (PMID 36788602, 2023). "By joint analysis of gene expression data from previous studies, we constructed interrelationships of mainly CRHBP, ICAM1, PLAGL1, DNMT1, CNTLN, DKK1, and EGR2 with preterm birth, infant disease, and breast cancer." (PMID 36788602, 2023). "Despite these constraints, we found a number of biologically meaningful, differentially expressed genes related to HIST1, HIST2 proteins, and some other such as PPARG, FGF2, APOB, CRHBP, CETP, and RXRG in breast cancer tissue compared to corresponding adjacent normal breast tissue." (PMID 21059268, 2010).
kidney cancer (2 papers, 2013 to 2016). Primary or metastatic malignant neoplasm involving the kidney. "We describe for the first time tumor specific epigenetic silencing of CRHBP and statistical association with aggressive tumors thus suggesting the CRH system to contribute to the development of kidney cancer." (PMID 27695045, 2016). "In conclusion our data give evidence that altered CRHBP expression as part of the UCN system is involved in kidney cancer." (PMID 23607589, 2013). "Expression of CRHBP on mRNA level has been reported in human normal kidney but there is still no data available about the expression of CRHBP in kidney cancer." (PMID 23607589, 2013).
bladder cancer (1 paper, 2016). "We found the CRHBP CGI to be frequently methylated in tumor cell lines of renal, prostatic, and bladder cancer." (PMID 27695045, 2016).
clear cell renal cell cancer (1 paper, 2016). "Here we investigated hypermethylation and epigenetic silencing of the CRH-Binding Protein (CRHBP) gene in clear cell renal cell cancer (ccRCC)." (PMID 27695045, 2016).
cocaine abuse (1 paper, 2023). Disorders related or resulting from use of cocaine. "Also, an association between a genetic variant in the CRHBP gene and reduction in cocaine abuse in methadone maintained participants has been reported." (PMID 37915799, 2023).
cognitive decline (1 paper, 2022). "Further machine learning data showed that increases in PRNP, CRHBP, VCP, and rGSK-3β(T/S9) (ratio of total to serine-9-phosphorylated glycogen synthase kinase-3β) had the greatest power to identify mild cognitive decline in T2DM patients." (PMID 36506101, 2022). "Further studies by ELISA and Peterson’s analyses validated that the upregulation of CIP2A, PRNP, and CRHBP and downregulation of VCP were indeed correlated to cognitive decline in T2DM patients." (PMID 36506101, 2022). "The bioinformatics data together indicate that upregulation of SERPINA1, VCP, PRNP, CIP2A, HSPA9, and UQCRC2 and downregulation of IGFBP3, CRHBP, PEPD, and GUSB were correlated to cognitive decline in T2DM patients." (PMID 36506101, 2022). "Among them, the increases in PRNP, CRHBP, VCP, and rGSK-3β(T/S9) had the greatest power to identify cognitive decline in T2DM patients." (PMID 36506101, 2022). "By integrating proteomics and machine learning data, we identified that changes in PRNP, CRHBP, VCP, and rGSK-3β had the greatest power to identify cognitive decline in T2DM patients." (PMID 36506101, 2022).
endometrial adenocarcinoma (1 paper, 2020). "CRHBP could also oppress proliferation of human endometrial adenocarcinoma cell line via activation of cAMP-PKA pathway." (PMID 31570754, 2020).
heroin dependence (1 paper, 2023). Physical and psychological dependence on the drug heroin. "Additionally, an interaction between life stress and variation in CRHBP has been reported as influential in heroin dependence relapse." (PMID 37915799, 2023).
hyperandrogenism (1 paper, 2022). Excessive secretion of androgens from the adrenal glands or gonads. "Corticotropin-releasing hormone-binding protein (CRHBP) is consistently the upregulated lncRNA with the highest fold-change in PCOS with hyperandrogenism compared to PCOS-free controls." (PMID 36498989, 2022).
Insulin resistance (1 paper, 2019). Increased resistance towards insulin, that is, diminished effectiveness of insulin in reducing blood glucose levels. "Corticotropin releasing hormone binding protein (CRHBP), ARHGEF15, MME, MAP1A, FGF13, and SHANK3 are novel biomarkers for the development of insulin resistance." (PMID 30678306, 2019).
liver cirrhosis (1 paper, 2017). "Notably, through literature reviews, we found that CLDN10, CDKN3, CRHBP and NEK2 were reported to be associated with HCC, and SPINK1 was associated with liver cirrhosis." (PMID 28036264, 2017).
mood disorder (1 paper, 2022). A cognitive disorder a disturbance in which the person's mood is hypothesized to be the main underlying feature. "Combined validation of independent datasets has shown that dysregulated mRNA expression of SST and CRHBP is shared in MDD-BP, and this plays a critical role in the etiology of mood disorders." (PMID 36081461, 2022).
renal tumor (1 paper, 2016). "Real-time impedance analysis was applied for analysis of invasiveness of renal tumor cells following si-RNA knockdown of CRHBP expression or ectopic expression of CRHBP." (PMID 27695045, 2016). "Our introductory functional analysis suggests that CRHBP may affect invasive behavior of kidney tumor cells therefore possibly explaining the statistical results." (PMID 27695045, 2016).